NTN1 (netrin 1)
Diseases named in the same sentence as NTN1 in open-access papers (continued):
Sharing a sentence is not in itself a finding about the gene and the disease.
endothelial dysfunction (3 papers, 2017 to 2023). In vascular diseases, endothelial dysfunction is a systemic pathological state of the endothelium (the inner lining of blood vessels) and can be broadly defined as an imbalance between vasodilating and vasoconstricting substances produced by (or acting on) the endothelium. "It is also possible that loss of direct Ntn1 signaling to arteries results in endothelial dysfunction and a failure to recruit smooth muscle." (PMID 37823339, 2023). "This is consistent with clinical findings of increased plasma Ntn1 levels in patients at risk of endothelial dysfunction compared to decreased Ntn1 concentrations in patients with progressed forms of atherosclerotic disease." (PMID 33511463, 2021). "In humans, ASS counteracts the reduction in plasma Ntn1 levels after vaccination-induced endothelial dysfunction, and the effect is directly related to the extent of cyclooxygenase inhibition." (PMID 33511463, 2021). "In conclusion, aspirin counteracts downregulation of netrin-1 following endothelial dysfunction due to its anti-inflammatory effect on the activated endothelium." (PMID 29156815, 2017). "In the current study, we investigated the effect of endothelial dysfunction on the circulating levels of netrin-1 in humans." (PMID 29156815, 2017). "We here explored the effect of aspirin on netrin-1 in healthy subjects undergoing influenza immunisation, which is an established experimental model of inflammation-related endothelial dysfunction." (PMID 29156815, 2017). "On the other hand, pharmacological inhibition of PGE2 as induced by the COX-inhibitor aspirin, also produced a small but significant decrease in netrin-1 levels, in the absence of endothelial dysfunction." (PMID 29156815, 2017).
kidney injury (3 papers, 2011 to 2026). Trauma to the kidney. "Netrin-1 has been identified as a biomarker for acute kidney injury in clinical settings." (PMID 41404576, 2025).
Myocardial fibrosis (3 papers, 2019 to 2025). "Most importantly, we established a strong negative correlation between cardiac Netrin-1 expression levels and collagen deposition, indicating a direct association between Netrin-1 depletion and the progression of myocardial fibrosis." (PMID 41531492, 2025).
pancreatitis (3 papers, 2012 to 2025). Inflammation of the pancreas. "The present study showed that our netrin-1 administration has protective and beneficial effects on the pancreas and lung in L-Arginin-induced pancreatitis model, as measured both biochemically and histologically." (PMID 23029434, 2012). "Given the possible upregulation of NTN1 during inflammation through the nuclear factor-kappa B (NF-κB) pathway, NTN1 might contribute to regeneration after pancreatitis by regulating innervation." (PMID 40777309, 2025). "To test this hypothesis, we used recombinant mouse netrin-1 to investigate the effects of netrin-1 during experimental pancreatitis." (PMID 23029434, 2012). "Furthermore, our RT-PCR and Western blot analyses showed that netrin-1 administration did not significantly inhibit the pancreatic expression of NF-κB in L-Arginin-induced pancreatitis." (PMID 23029434, 2012).
prostate carcinoma (3 papers, 2018 to 2020). A carcinoma that arises from epithelial cells of the prostate gland. "The levels of serum and urine levels of AMACR and Netrin 1 were 10.2 ±9.8 ng/mL; 6.8 ±2.5 ng/mL; 159.1 ±44.1 pg/mL and 20.1 ±5.3 pg/mL respectively in prostate cancer group." (PMID 30104809, 2018). "Accordingly, netrin-1 could be a promising therapeutic agent against prostate carcinoma." (PMID 30104809, 2018).
renal cell carcinoma (3 papers, 2018 to 2025). "Human renal cell carcinoma sunitinib-conditioned cell lines showed upregulation of netrin-1 in microarray and q-PCR." (PMID 29854303, 2018). "Netrin-1 is highly upregulated in renal cell carcinoma treated with sunitinib, but has no influence on cell viability or cell migration in metastatic RCC." (PMID 29854303, 2018).
renal failure (3 papers, 2011 to 2021). "Based on previous studies showing that netrin-1 is induced during conditions of limited oxygen availability (hypoxia), and dampens hypoxia-induced inflammation, we hypothesized a role for endogenous netrin-1 in dampening renal failure after AKI." (PMID 21625583, 2011).
small fiber neuropathy (3 papers, 2021 to 2022). "In patients suffering from small fiber neuropathy, axon guidance cue netrin-1 is highly expressed in patients’ keratinocytes which can reduce sensory neurite outgrowth." (PMID 35058747, 2021). "Proteins and mRNA do not always correspond; this, for example, can also be seen for Cldn2 in intestinal ischemia or NTN1 in keratinocytes and immunoreactivity in skin samples from patients with small fiber neuropathy." (PMID 34576252, 2021). "In contrast, increased netrin-1 immunoreactivity from keratinocytes from small fiber neuropathy patients is supposed to promote fiber degeneration in the skin." (PMID 34576252, 2021).
spinal cord injury (3 papers, 2017 to 2022). Penetrating and non-penetrating injuries to the spinal cord resulting from traumatic external forces (e.g., WOUNDS, GUNSHOT; WHIPLASH INJURIES; etc.). "Our previous findings indicated that treatment with Netrin-1 could improve functional recovery through the stimulation of autophagy, by activating the AMP-activated protein kinase/mammalian target of rapamycin (AMPK/mTOR) signaling pathway in rats following spinal cord injury (SCI)." (PMID 29209172, 2017).
acute coronary syndrome (2 papers, 2020 to 2022). Signs and symptoms related to acute ischemia of the myocardium secondary to coronary artery disease. "Only one study has attempted to assess the diagnostic and prognostic value of serum Netrin-1 levels in patients undergoing coronary angiography for acute coronary syndromes." (PMID 36009485, 2022). "There are no human studies about Netrin-1 in acute coronary syndrome (ACS)." (PMID 32455061, 2020).
age-related macular degeneration (2 papers, 2015 to 2022). Age-related loss of vision in the central portion of the retina (macula), secondary to retinal degeneration. "For instance, netrin-1-DCC signaling systems were associated with age-related macular degeneration and FOXP2 was associated with age-dependent dormant resident progenitors." (PMID 35017462, 2022).
anaplastic astrocytoma (2 papers, 2017). "Within astrocytomas 77.8%, within anaplastic astrocytomas 62.5% and within GBMs 77.1% of the tumors were NTN1 positive whereas within oligodendrogliomas and oligoastrocytomas only 26.7% and 36.8%, respectively, were NTN1 positive." (PMID 28069038, 2017).
astrocytoma (2 papers, 2017 to 2025). "Comparison of the grade 3 astrocytoma to the matched normal sample, revealed the top three DEGs encoding ECM glycoproteins (NTN1, AEBP1 and SPARC) and ECM-affiliated factors (C1QA, LGALS9 and C1QL1)." (PMID 41366031, 2025).
bone cancer (2 papers, 2023 to 2025). A primary or metastatic malignant neoplasm affecting the bone or articular cartilage. "As expected, miR-PC-2869 regulates the expression of CDK8, EEF1A1, and NTN1 in both human bone cancer and deer antler cells, suggesting that conserved target sites underlie the cross-species regulation of miR-PC-2869." (PMID 37446017, 2023). "In adult disease models, aberrant netrin-1: DCC signaling drives pathological nerve sprouting and pain: for example, in a rat bone cancer pain model, tumor-derived netrin-1 activates DCC to promote nociceptive neuron sprouting, and DCC inhibition attenuates hyperalgesia." (PMID 40728980, 2025). "Notably, cyclin-dependent kinase 8 (CDK8), eukaryotic translation elongation factor 1 alpha 1 (EEF1A1), and netrin 1 (NTN1), three functional targets of miR-PC-2869, jointly mediate the cellular functions of miR-PC-2869 in antler growth and bone cancers." (PMID 37446017, 2023).
brain injury (2 papers, 2017 to 2022). Acute and chronic (see also brain INJURIES, CHRONIC) injuries to the brain, including the cerebral hemispheres, CEREBELLUM, and brain STEM. "We aimed to investigate the ability of the DCC receptor and Netrin-1 to predict a high ICP level after operation in severe traumatic brain injury and their prognostic significance." (PMID 35806983, 2022). "Although netrin-1 has been previously investigated in middle cerebral artery occlusion and traumatic brain injury models, there is no information regarding the role of netrin-1 in ICH-induced SBI." (PMID 29375318, 2017).
Cirrhosis (2 papers, 2016 to 2025). A chronic disorder of the liver in which liver tissue becomes scarred and is partially replaced by regenerative nodules and fibrotic tissue resulting in loss of liver function. "To address the specific role of HCV in our model and distinguish fibrosis-associated Netrin-1 induction from HCV-associated Netrin-1 induction, we plotted Netrin-1 mRNA levels in HCV+ versus HCV- samples against all (F0 to F4/cirrhosis) histological stages." (PMID 27031829, 2016). "It is likely to be most relevant at the cirrhosis level, a harsh environment for hepatocytic survival, which displays the highest level of Netrin-1 signals, and even more so upon HCV infection." (PMID 27031829, 2016). "Taken together, these data suggest that Netrin-1 expression is induced in patients chronically infected with HCV across all stages of the disease, and that HCV and cirrhosis cooperate for higher Netrin-1 induction." (PMID 27031829, 2016). "Importantly, a comparison of HCV(-) biopsies revealed that HCV-negative cirrhosis (i.e., F4) samples already displayed the highest 4-fold to 12-fold increase in Netrin-1 mRNA compared to all other HCV-negative samples." (PMID 27031829, 2016). "As in the rat, neurogenic netrin-1 expression was strongly (r >0.85) correlated with proteolyzed β-tubulin and DCX levels, as well as cirrhosis onset, and HCC." (PMID 39717507, 2025). "Both cirrhosis and HCV contributed to the induction of Netrin-1 expression, whereas anti-HCV treatment resulted in a reduction of Netrin-1 expression." (PMID 27031829, 2016). "Furthermore, Netrin-1 was upregulated in all histological stages of HCV+ hepatic lesions, from minimal liver fibrosis to cirrhosis and HCC, compared to histologically matched HCV- tissues." (PMID 27031829, 2016).
disc degeneration (2 papers, 2024 to 2025). "In this loss of function study, the authors used a CRISPR-Cas9 system, targeting the Ntn1 (Netrin 1) gene to deplete Netrin-1 in vivo, by AAV injection, in a rat model of disc degeneration." (PMID 40406584, 2025).
experimental autoimmune encephalomyelitis (2 papers, 2021 to 2022). An autoimmune demyelinating disease of the central nervous system that is produced experimentally in animals by the injection of homogenized brain or spinal cord in Freund's adjuvant. "The expression of Netrin-1 protein in the spinal cord of rats with experimental autoimmune encephalomyelitis (EAE) was studied by a Korean research team." (PMID 35493300, 2022).
glaucoma (2 papers, 2021). Increased pressure in the eyeball due to obstruction of the outflow of aqueous humor. "Netrin-1 is involved not only in glaucoma but also in cancer." (PMID 34646884, 2021).
hemorrhage stroke (2 papers, 2021 to 2024). "To investigate whether peptide E1 derived from Netrin-1 play an important role in functional recovery after hemorrhage stroke, we established an experimental ICH model in mice by injecting collagenase mixed with ink into the striatum." (PMID 34063230, 2021).
hepatitis C (2 papers, 2016 to 2022). "It would be interesting to characterize this pathway in EBOV-infected Huh7 cells, especially Netrin-1, to ascertain whether, as in Hepatitis C virus infection, the level and translation of Netrin-1 are likewise augmented in the context of EBOV infection." (PMID 35563619, 2022).
hypoxic-ischemic encephalopathy (2 papers, 2021 to 2025). "In 75 hypoxic-ischemic encephalopathy patients, correlations of Netrin-1 with lactate, uric acid, and lactate dehydrogenase were statistically significant (p=0.0001, 0.008, and 0.043, respectively)." (PMID 40531771, 2025). "Serum Netrin-1 concentrations were significantly greater in patients with moderate and severe hypoxic-ischemic encephalopathy who underwent therapeutic hypothermia than in controls and patients with severe hypoxic-ischemic encephalopathy." (PMID 40531771, 2025). "Demographic, laboratory, and Netrin-1 data were evaluated for all hypoxic-ischemic encephalopathy stages." (PMID 40531771, 2025). "It was hypothesized that Netrin-1 will differ at different hypoxic-ischemic encephalopathy stages." (PMID 40531771, 2025). "However, serum Netrin-1 concentrations were not significantly greater in patients with mild hypoxic-ischemic encephalopathy than in controls." (PMID 40531771, 2025).
intestinal tumor (2 papers, 2020 to 2022). "Nevertheless, netrin-1 expression in the mouse gut reduced intestinal cell apoptosis and facilitated intestinal tumor development." (PMID 32902412, 2020). "Contrary to the effect of Netrin-1, DCC acts as an inhibitor of cell invasion, tumor growth and metastasis 75, and limits the progression of intestinal tumors in mouse models." (PMID 36147476, 2022).
intracerebral hemorrhage (2 papers, 2017 to 2025). A cerebrovascular disorder characterized by bleeding into one or both cerebral hemispheres including the basal ganglia and the cerebral cortex. "This study aimed to identify the roles of netrin-1 and KIF1A in secondary brain injury after intracerebral hemorrhage (ICH) and the potential mechanisms." (PMID 29375318, 2017).
ischemia reperfusion injury (2 papers, 2011 to 2025). Adverse functional, metabolic, or structural changes in ischemic tissues resulting from the restoration of blood flow to the tissue (reperfusion), including swelling; hemorrhage; necrosis; and damage from free radicals. "Indeed, Arrb2 regulates LPS-induced inflammatory response and endotoxemia, while Ntn1 can minimize inflammatory damage associated with ischemia-reperfusion injury." (PMID 22241984, 2011). "Netrin-1 has demonstrated cardioprotective effects in ischemia-reperfusion injury (IRI) following MI." (PMID 41531492, 2025).
kidney cancer (2 papers, 2020 to 2025). Primary or metastatic malignant neoplasm involving the kidney. "However, only NTN1 was previously associated with the occurrence and development of kidney cancer and non-small cell lung cancer." (PMID 32251318, 2020). "This may indicate that the carcinogenic mechanism of NTN1 and NTNG1 in pan-kidney cancers is related to promoter methylation." (PMID 32251318, 2020).
kidney damage (2 papers, 2018 to 2021). "This property caused recognition of netrin-1 as an early diagnostic marker of kidney damage." (PMID 33669495, 2021). "We showed that the netrin-1/creatinine ratio is increased in premature babies which may have potential diagnostic value in the diagnosis of subclinical kidney damage in premature newborns." (PMID 33669495, 2021). "In recent publications, netrin-1 seems to be a promising biomarker of kidney damage in different pathological states." (PMID 33669495, 2021).
lip (2 papers, 2020 to 2024). "Interestingly, a variant of NTN1 (rs4791331) has been associated with an increased risk of left cleft lip with or without cleft palate." (PMID 38534778, 2024). "Conditioning on three genome-wide significant loci, rs16957821 was identified within NTN1 at 17p13.1 (p-value = 1.40 × 10−7), which had been previously reported by CL/P and OFC (cleft lip and/or palate) GWAS and replication studies." (PMID 33137956, 2020).
liver fibrosis (2 papers, 2016 to 2026). "Functional studies showed that adenovirus-associated virus (AAV)-mediated hepatic Netrin-1 overexpression exacerbated fibrosis, whereas HSC-specific conditional ablation of Netrin-1 markedly attenuated diet-induced MASH and CCl4-induced liver fibrosis." (PMID 41514498, 2026). "Hepatic Netrin-1 expression was consistently elevated across multiple experimental models of liver fibrosis." (PMID 41514498, 2026). "Notably, lipid nanoparticle-mediated siRNA knockdown of Netrin-1 ameliorated liver fibrosis in mice." (PMID 41514498, 2026). "Here, we identify Netrin-1 as an autocrine factor that drives HSC activation and liver fibrosis in patients with MASH." (PMID 41514498, 2026).
lymph node metastasis (2 papers, 2023 to 2025). "Netrin-1 was significantly higher in CRC with liver metastasis who had Dukes stage C, low differentiation and lymph node metastasis than these with Dukes stage A + B, moderately high differentiation and no lymph node metastasis (P < 0.05)." (PMID 37568074, 2023).
mantle cell lymphoma (2 papers, 2022 to 2024). Mantle cell lymphoma is a rare form of malignant non-Hodgkin lymphoma affecting B lymphocytes in the lymph nodes in a region called the ``mantle zone''. "In human diffuse large B‐cell lymphoma (DLBCL) and mantle cell lymphoma (MCL) biopsies tissues, upregulation of the NTN1/DCC expression ratio tipped the scales towards loss of DCC‐induced apoptosis." (PMID 38546656, 2024). "In humans, expression of netrin-1 detected by RT-qPCR in mantle cell lymphomas and DLBCL was increased compared with tonsillar non-neoplastic samples (14 and 4.2 times superior, respectively)." (PMID 36136711, 2022).
metastatic disease (2 papers, 2018). "Therefore, suggesting that there are other factors other than netrin-1 that is responsible for metastatic disease in RCC." (PMID 29854303, 2018). "Therefore, a balance of netrin-1 and SEMA3F in tumor cells might be a diagnostic and prognostic biomarker for a high metastatic tumor." (PMID 30532711, 2018).
microphthalmia (2 papers, 2019 to 2025). Congenital or developmental anomaly in which the eyeballs are abnormally small. "Here, we report the first patient with chorioretinal coloboma and microphthalmia harbouring a novel heterozygous likely pathogenic NTN1 missense variant, c.1483T>A p.(Tyr495Asn), validating a conserved gene function in ocular development." (PMID 39648562, 2025). "Evidence of NTN1 function in optic fissure closure was provided by an ocular coloboma phenotype in zebrafish where ntn1a was knocked down or knocked out, with the latter also showing microphthalmia." (PMID 39648562, 2025).
neuropathy (2 papers, 2021 to 2022). A disorder affecting the nervous system that manifests with pain, tingling, numbness, and/or muscle weakness. "The present study extends earlier findings by showing that a single intrathecal dose of netrin-1 does not only induce acute hypersensitivity in rodents, but it may induce a prolonged neuropathy-like pain hypersensitivity condition lasting at least up to three weeks." (PMID 35743067, 2022). "Due to the lack of netrin-1 protein, we hypothesized that exogenous netrin-1 might improve neuropathic pain and neuropathy." (PMID 34576252, 2021).
renal fibrosis (2 papers, 2016 to 2025). A final common manifestation of a wide variety of chronic kidney diseases characterized by glomerulosclerosis and tubulointerstitial fibrosis. "Our findings establish a novel TCF3-Netrin-1-autophagy regulatory axis that contributes to renal fibrosis in experimental DN models." (PMID 41404576, 2025). "Netrin-1 can therefore be considered as a potential therapeutic agent for the treatment of renal fibrosis." (PMID 27176224, 2016). "In our previous study, we reported that netrin-1 appears to be mediated by preservation of PTC endothelium and is associated with partial reversal of impaired angiogenesis, which reduce renal fibrosis in the 5/6 Nx rat model of kidney disease." (PMID 27176224, 2016). "Our study found that netrin-1 pretreatment resulted in blocking of EndoMT in 5/6 Nx rats; however, the mechanism via which netrin-1 attenuates renal fibrosis by blocking EndoMT remains largely unknown." (PMID 27176224, 2016). "EndoMT contributes to renal fibrosis in 5/6 Nx rats and can be prevented by netrin-1 treatment." (PMID 27176224, 2016).